ELAVL1 (ELAV like RNA binding protein 1)
Diseases named in the same sentence as ELAVL1 in open-access papers (continued):
Sharing a sentence is not in itself a finding about the gene and the disease.
cancer (continued). "Also, only two cell lines were used, which had some different responses to AHR and ELAVL1 modulation; so, further investigation into the mechanisms causing such differences and the stratification of cancer subtypes that would benefit most from such modifications are required." (PMID 37685961, 2023). "We demonstrated that G-patch domain of CMTR1 and Hinge domain of ELAVL1 were required for their interaction, suggesting their interplay in cancer progression." (PMID 39815331, 2025). "ELAVL1 (human antigen R, HuR) is an RNA-binding protein that plays a crucial role in the development and progression of various cancers." (PMID 40958880, 2025). "ELAVL1 is highly expressed in cancer cells and is also involved in inflammation by regulating mRNA stability, splicing, and translation." (PMID 40251596, 2025). "In cancer research, ELAVL1 has also been reported to interact with molecules such as YTHDC1 and IGF2BP1 to synergistically stabilize RNA." (PMID 40958880, 2025). "Overexpression of HCP5 stabilizes ferroptosis-related genes via the HCP5-132aa/YBX1/ELAVL1 ternary complex, suppressing ferroptosis and accelerating cancer progression." (PMID 41304936, 2025). "By recruiting mRNA stabilizers such as ELAV-like RNA-binding protein 1 (ELAVL1) in cancer and poly(A)-binding protein cytoplasmic 1a (Pabpc1a) in zebrafish embryogenesis, YBX1 facilitates the stability of m5C-labelled transcripts." (PMID 39574165, 2024). "Overall, a comprehensive understanding of the omnidirectional mechanism of ELAVL1/HuR-miRNA interplay should be considered to improve the development of cancer therapeutics." (PMID 38689093, 2024). "ELAVL1 overexpression or overactivation is known to correlate with high-grade malignancy, drug resistance and poor prognosis in many cancers." (PMID 38306394, 2024). "Cell stresses, including oxidative stress and cancer therapy-induced stress, have been reported to regulate alternative RNA splicing via the Hu antigen R (HuR), also known as ElavL1." (PMID 36982267, 2023). "ELAVL1 is a member of the ELAVL family of RNA-binding proteins, which contain several RNA recognition motifs, and ELAVL1 overexpression has been observed in several cancers." (PMID 38067275, 2023). "Thousands of mRNAs are ELAVL1 targets, including factors fostering diverse cancer traits such as proliferation (cyclins A2, B1, D1, and E1), angiogenesis (HIF1a, PTGS2, and VEGFA), survival (BCL2 and MCL1), and invasion (MMP9 and SNAI1)." (PMID 37298909, 2023). "ELAV like RNA binding protein 1 (ELAVL1), which is highly expressed in many cancers, was a key target of ferroptosis induced by Erastin or Sorafenib in hepatic stellate cells." (PMID 35663406, 2022). "The protein ELAVL1 plays an essential role in several biological processes such as proliferation, cell cycle, and cancer growth." (PMID 36477660, 2022). "In malignant peripheral nerve sheath tumors, the RBP HuR/ELAVL1 is highly expressed and drives tumor metastasis by interacting with multiple cancer-related transcripts." (PMID 36614043, 2022). "What’s more, IGF2BP3/ELAVL1 complex leads to prolonged half-lives of cancer-related mRNA molecules and increased expression of the target genes." (PMID 35276059, 2022). "HuR/ELAVL1 (embryonic lethal abnormal vision 1) was a downstream target of miR-29b in some cancer cells." (PMID 35986311, 2022). "ELAVL1 targets include proto-oncogenes, growth factors, and invasive factors; thus, it plays an essential role in cancer." (PMID 36324584, 2022). "On the other hand, dysregulation of the expression of the ELAVL1 gene or the activity of the protein can also lead to aberrant cellular growth and cancer." (PMID 35465324, 2022). "In PCa, it was reported that normal prostate epithelium had mild to moderate predominantly nuclear immunostaining of ELAVL1 and both higher cytoplasmic and nuclear expression in cancer cells." (PMID 35978821, 2022).
cancer (continued). "ELAV Like RNA Binding Protein 1 (ELAVL1), also known as HuR, is highly expressed in several cancers, and can be applied in cancer diagnosis, prognosis, and therapy." (PMID 33602031, 2021). "Multiple studies have demonstrated the essential role of ELAVL1 in the development of biological progression via the modulation at post-transcriptional mode, such as cancer metastasis, autophagy and others." (PMID 34234645, 2021). "In our study, BCAR4 was proved to bind miR-139-3p thereby targeting ELAVL1, which was consistent with a previous research that miR-139-3p inhibited cancer progress by reducing ELAVL1 expression." (PMID 33602031, 2021). "ELAVL1 is a cancer‐related RNA‐binding proteins (RBPs) and plays an oncogenic role in the progression of various cancers." (PMID 34409736, 2021). "On the contrary, high level of HuR (Elavl1) expression within the same GEO dataset correlated with the prolonged survival of cancer patients." (PMID 34091597, 2021). "Numerous studies have indicated that cytoplasmic accumulation of ELAVL1 has a link to multidrug resistance (MDR) acquired after chemotherapy and therefore causing poor prognosis in various cancer types." (PMID 31440515, 2019). "Though ELAVL1 (HuR) is a well-studied protein, limited reports exist for roles of the other three family members in cancers." (PMID 28035070, 2017). "Of the many RBPs that bind to the KRAS 3′ UTR, AGO2, HuR (or ELAVL1), IGF2BP1/2/3, PUM2, EWSR1, TAF15, FUS, and TIA1 have been previously implicated in cancer." (PMID 26930719, 2016). "Using our algorithm, we also observed the over-representation of the binding sites of RBMX, SFRS1 and ELAVL1 in the set of enriched exosomal lncRNAs in cancer cell lines and in the healthy cells." (PMID 27102850, 2016). "In fact, ELAVL1 stabilizes a variety of target mRNAs, especially mRNAs related to cancer and inflammation." (PMID 26459019, 2015). "Recently, it was shown that HSF1 is involved in the regulation of mRNA-binding protein ELAVL1 (HuR) which, in turn, controls mRNA stability and/or translation of many proteins involved in cancer." (PMID 24165036, 2013). "Currently, targeting Elavl1 is considered a promising therapeutic strategy in cancer treatment." (PMID 40000387, 2025). "The expression of Elavl1 is an important prognostic marker for benign and malignant tumours." (PMID 40000387, 2025). "This discrepancy likely stems from the following: (i) methodological differences (subtype-stratified IHC vs. pan-cancer mRNA sequencing) and (ii) post-transcriptional regulation by ELAVL1, which stabilizes CELF1 protein in aggressive subtypes, as observed in oral SCCs." (PMID 41306913, 2025). "In addition to its role in the nervous system, Elavl1 also plays a crucial role in inflammation and cancer." (PMID 40000387, 2025). "Elavl1 is the most extensively studied member of the Elav protein family in cancer research." (PMID 40000387, 2025). "Therefore, ELAVL1 is considered a promising target for cancer treatment, and numerous studies have investigated the therapeutic effects of inhibiting ELAVL1." (PMID 39390359, 2024). "In cancer biology, ELAVL1 influences tumor proliferation, migration, and drug resistance." (PMID 38981872, 2024). "In addition, ELAVL1 can interact with thePTBP1 3’UTR to enhance the stabilization of PTBP1incolorectal cancer." (PMID 38394156, 2024). "Additionally, a substantial body of research has demonstrated a strong correlation between ELAVL1 expression and the malignant potential, tumor growth, and invasive capabilities of various types of cancer." (PMID 39390359, 2024). "Although the role of HuR in cancer has been established, until recently, there have been no reported Single Nucleotide Polymorphisms (SNPs) in the HuR gene (ELAVL1) associated with cancer onset in patients." (PMID 39695179, 2024). "ELAVL1 as an m6A reader positively correlates with Reptin in 32 types of cancer." (PMID 35754815, 2022).
cancer (continued). "ELAVL1 expression is higher in almost all cancer tissues than in healthy ones." (PMID 36324584, 2022). "The high frequency of simultaneous nucleocytoplasmic expression of ELAVL1 in HCC tissues might suggest that it is closely involved in the post-translational modification of many cancer-related genes." (PMID 35887229, 2022). "ELAVL1, which is also called HuR, has been widely investigated in many cancers as an RBP." (PMID 34911544, 2021). "On the other hand, CCAT2 interacts with the RNA binding protein (RBP) ELAVL1/HuR at the nuclear level, a key factor involved in mRNA stabilization, previously shown to promote proliferation, apoptosis, and differentiation in multiple types of cancer." (PMID 34830370, 2021). "ELAVL1, also known as Hu antigen R (HuR), is an abundant RNA binding protein that can affect the stability and translation of many RNAs and participate in the regulation of chronic inflammation and cancer progression." (PMID 32724827, 2020). "In addition, while nuclear ELAVL1 was important in cancer progression, cytoplasmic ELAVL1 was also identified as an independent prognostic factor for survival in NSCLC38." (PMID 32170141, 2020). "No somatic ELAVL1 mutations, copy number changes, or epigenetic alterations in any human cancer have been reported to date." (PMID 26314962, 2015). "ELAVL1/HuR showed remarkable centrality, interacting specially with genes harboring non-synonymous SNVs thus reinforcing the proposition of targeted mutagenesis in cancer pathways." (PMID 26442106, 2015). "Interestingly, ELAVL1 was found to be up-regulated and preferentially localized to the cytoplasm in multiple cancer cell lines (including MCF7), which correlates with carcinogenesis and poor prognosis." (PMID 24417896, 2014). "Therefore, we speculate that competitive binding of CMTR1 and TRN2 might regulate nuclear retention of ELAVL1 in cancer cells, which warrants further investigation." (PMID 39815331, 2025). "Furthermore, this provides us with insights for targeted cancer therapy against ELAVL1." (PMID 39390359, 2024). "Thus, ELAVL1 has emerged as an attractive drug target for cancer therapy." (PMID 38306394, 2024). "Mice lacking ELAVL1 in myeloid-lineage cells, which include many of the innate immune system cells, showed a rapid progression of chemical-induced colitis and increased susceptibility to endotoxemia and colitis-associated cancer." (PMID 31440515, 2019). "Some RBPs like LIN28A/B, ELAVL1, IGF2BP or MUSASHI proteins also exhibit long-standing and well-characterized roles in carcinogenesis or tumour suppression in other cancer types." (PMID 40427100, 2025). "Overall, these findings indicate that ELAVL1/HuR can compete with miR-122 for binding to CAT-1 mRNA, thus promoting cancer progression in HCC 6,76." (PMID 38689093, 2024). "Hu-antigen R (HuR), also known as ELAVL1, is one of the most well-understood RBPs involved in the tumorigenesis of numerous cancers." (PMID 38443362, 2024). "Specifically, we have identified that ELAVL1 enhances HMGB3 mRNA stability and regulates the Wnt/β-catenin signaling pathway, thereby promoting glycolysis in cancer cells." (PMID 39390359, 2024). "ELAVL1, a ubiquitously expressed neuron-like ELAV protein, participates in various biological behaviors of cancer." (PMID 38956466, 2024). "Hypoxia increases ELAVL1 by HIF-1 upregulation, and ELAVL1 then combines with SLC7A11 to improve the expression of SLC7A11, thereby promoting cancer cells growth by inhibiting ferroptosis." (PMID 37458878, 2023). "In the present study, cell growth in HepAD38 cells was impaired in the ELAVL1-knockdown group independently of HBV replication, but HBx specifically affects the transcription of various cancer-related genes and enhances cell proliferation and capability." (PMID 35887229, 2022). "We observed that AGO1/2, EIF4A3, ELAVL1, and PTBP1 were the main RBPs acting in most of the cancer-related and gene regulation enriched pathways." (PMID 35805051, 2022).
cancer (continued). "We find genes, such as TK1 in LUAD and ELAVL1 in BRCA, predicted in only one sample but known to have a role in respective cancer types." (PMID 35620468, 2022). "This miRNA plays a role in decelerating in vitro cell proliferation, migration, and in vivo cancer growth by targeting multiple oncogenes, such as hypoxia-inducible factor 1α (HIF-1α) and ELAV-like RNA binding protein 1 (ELAVL1)." (PMID 33066509, 2020). "In conclusion, DRG1 exerted cancer-promoting effects on OS, and up-regulated DRG1 in OS was induced by METTL3 and ELAVL1 in an m6A-dependent manner." (PMID 32266933, 2020). "Hu antigen R (HuR), also known as embryonic lethal abnormal vision 1 (ELAVL1), is one of the most famous cancer-related RBPs." (PMID 29351796, 2018). "We discovered that blocking the interaction of CMTR1 with ELAVL1 via SNORA37 knockdown was able to repress tumorigenesis and aggressiveness, indicating the value of SNORA37/CMTR1/ELAVL1 axis as a therapeutic target for cancers." (PMID 39815331, 2025). "Secondly, it reduces Ubiquitin Specific Peptidase 4 (USP4) expression, leading to the degradation of ELAV Like RNA Binding Protein 1 (ELAVL1) protein and subsequently increasing Rho GDP Dissociation Inhibitor Alpha (ARHGDIA) levels, promoting cancer cell invasion and migration." (PMID 38711100, 2024). "The functional group of RNA binding proteins included ELAVL1, ZRANB2 and HNRNPA1, whose role in alternative splicing of transcripts to serve tumour development have made them a focus of recent efforts to target altered RNA splicing in cancer." (PMID 37997254, 2024). "Moreover, we observed changes in the abundance of ELAVL1 and STAT3, which are activated in skeletal muscle and promote skeletal muscle atrophy in cancer." (PMID 35563153, 2022). "LncRNA breast cancer antiestrogen resistance 4 (BCAR4) knockdown induces cell apoptosis and G1/S arrest, while represses cell proliferation and migration in ESCA by sponging miR-139-3p to upregulate ELAV like RNA binding protein 1 (ELAVL1)." (PMID 34516362, 2021). "Similarly, downstream targets of the AMPK pathway including the RNA binding protein (Elavl1), CREB binding protein (Crebbp), and the stimulatory G-protein alpha subunit (Gnas), known to be elevated in various cancers, were downregulated by BRB administration." (PMID 31336728, 2019). "It interacts with several large hubs such as MAP2K1, ELAVL1 and PAPOLA1 in the PPI network, and therefore may play important roles in insensitivity of BC cells to cancer drugs." (PMID 28481952, 2017). "We did not identify any RBP which uniquely target either the exosomal or the cellular lncRNAs, however there is a significant difference in the number of binding sites for RBMX, ELAVL1 and SFRS1 in the exosomal lncRNAs compared to cellular lncRNAs of both healthy and cancer cell lines." (PMID 27102850, 2016). "Importantly, we detected increased mRNA half-lives for cancer-related transcripts such as CCNA2, CCNB2 and CDKN1A that were previously shown to be stabilized by ELAVL1." (PMID 24417896, 2014). "The positive pan-cancer correlations with m1A RNA methylation regulatory proteins YTHDF2 and ALKBH1, m5C methylation regulatory proteins DNMT1, DNMT3B, and ALYREF, and m6C RNA methylation regulatory proteins HNRNPC, HNRNPA2B1, and ELAVL1 were particularly significant." (PMID 36090896, 2022). "In addition, ELAVL1 and PTBP2 also participate in cancer progression via AS function." (PMID 33281863, 2020). "Using a set of 19 lncRNAs which were common to all cancer cell lines but not enriched in exosomes, we found a significant reduction (p value = 0.001) in enriched binding sites for both RBMX and ELAVL1." (PMID 27102850, 2016).
tumor (336 papers, 2006 to 2026). "For example, in ductal breast carcinoma, increased cytoplasmic Elavl1 is associated with poor differentiation, larger tumour size, lower survival rates, and resistance to radiotherapy and chemotherapy." (PMID 40000387, 2025). "Many of the ELAVL1 target mRNAs encode proteins important for cell growth, tumorigenesis, angiogenesis, tumor inflammation, invasion and metastasis." (PMID 38306394, 2024). "Conversely, cytoplasmic ELAVL1 expression has been reported to be associated with aggressive tumor phenotype." (PMID 35887229, 2022). "Human antigen R (HuR) is an RNA binding protein encoded by the ELAVL1 gene, which plays an important role in facilitating tumor survival, invasion and resistance." (PMID 36139078, 2022). "Moreover, several studies have confirmed the close association of m6A regulatory factors ALKBH5, WTAP, and ELAVL1 with the pathological process of tumor invasion and metastasis." (PMID 37684273, 2023). "ELAVL1 codes for an RNA binding protein controlling multiple facets of carcinogenesis, and literature reports show its over-expression to be associated with adverse-event free tumours." (PMID 34193143, 2021). "The direct interactions between ELAVL1 and mutated genes in tumor samples are shown in." (PMID 26442106, 2015). "According to data from TCGA database, ELAVL1 expression is higher in most PCa samples than in adjacent normal tissues, and its expression increases with an increasing Gleason score, indicating that elevated ELAVL1 expression is closely associated with tumor progression in PCa." (PMID 40958880, 2025). "In summary, ELAVL1 is a key oncogene in PCa that promotes tumor proliferation and metastasis while inhibiting apoptosis through multiple mechanisms, including stabilizing mRNAs and circRNAs and regulating m6A modifications." (PMID 40958880, 2025). "Elavl1 is also involved in various physiological processes, including cellular senescence, tumour growth, stress responses and apoptosis, neuroinflammation, and motor neuron injury." (PMID 40000387, 2025). "Our TMA results further showed that ELAVL1 expression increased significantly with tumor stage and was positively correlated with BAP31 expression." (PMID 39990675, 2025). "Our lab has shown that the tumor-intrinsic RNA-binding protein human antigen R (HuR; ELAVL1) plays an important role in reshaping the tumor microenvironment by regulating the stability and translation of cell communication–encoding transcripts." (PMID 40814996, 2025). "Another class of related genes with similar roles is RNA-binding proteins (RBPs), such as the widely expressed HuR (ELAVL1), whose expression is upregulated in tumors and promotes tumor growth." (PMID 40801655, 2025). "In conclusion, ELAVL1 mRNA levels are enhanced in BRCA tumor samples compared to normal tissues, and increased ELAVL1 levels are related to poor prognosis in patients." (PMID 38965208, 2024). "Subsequently, we evaluated tumorigenic conditions in mice and observed that the downregulation of ELAVL1 remarkably hindered graft tumor growth, as indicated by reduced tumor size, tumor growth curve and weight." (PMID 39390359, 2024). "A subcutaneous tumor model was established in nude mice to investigate the role of ELAVL1 in tumor progression." (PMID 39390359, 2024). "The functional role of ELAVL1 in tumor development was investigated by establishing stable mouse transplants with ELAVL1-silenced HONE-1 cells." (PMID 39390359, 2024). "Immunohistochemical assessment of mouse tumor tissues further supported these findings, revealing a notable decrease in Ki67 expression upon ELAVL1 knockdown." (PMID 39390359, 2024). "We compared the expression of ELAVL1 in 21 tumor studies with paired normal data available from the TCGA databank." (PMID 38965208, 2024). "The expression of ELAVL1 was observed to be markedly upregulated in head and neck squamous carcinoma in comparison to non-tumor tissues, as evidenced by data extracted and analyzed from the UALCAN database." (PMID 39390359, 2024).